KMT2A (lysine methyltransferase 2A)
Diseases named in the same sentence as KMT2A in open-access papers (continued):
Sharing a sentence is not in itself a finding about the gene and the disease.
cervical cancer (4 papers, 2017 to 2023). A primary or metastatic malignant neoplasm involving the cervix. "We also identified the underlying molecular mechanisms of KMT2A in cervical cancer and its clinical significance." (PMID 32436862, 2020). "To identify the underlying molecular mechanism of KMT2A in regulating cervical cancer cell growth, we analyzed the effect of KMT2A on the expression of a series of apoptosis-related proteins." (PMID 32436862, 2020). "In our study, we also showed that the expression levels of KMT2A is negatively associated with the differentiation grade of cervical cancer." (PMID 32436862, 2020). "For example, the knockdown of KMT2A in cervical cancer cells (HeLa) using antisense RNA resulted in increased apoptosis." (PMID 33302406, 2020). "Knockdown of KMT2A significantly suppressed cell proliferation and migration and induced apoptosis in cervical cancer cells, accompanying with activation of PARP/caspase pathway and inhibition of VADC1." (PMID 32436862, 2020). "We also analyzed the relationships of different clinicopathologic variables with KMT2A/VDAC1 expression in cervical cancer patients." (PMID 32436862, 2020). "In this study, we have demonstrated the functional significance of KMT2A in cervical cancer progression in vitro and in vivo." (PMID 32436862, 2020). "The in vivo results from a cervical cancer xenograft mouse model also validated that KMT2A knockdown suppressed tumor growth by inhibiting VDAC1, whereas KMT2A overexpression promoted cervical cancer growth." (PMID 32436862, 2020). "We also found that a series of apoptosis-related proteins were affected by KMT2A knockdown in cervical cancer cells." (PMID 32436862, 2020). "In this study, we investigated the role of KMT2A on cervical cancer cell growth, cell migration and cell apoptosis via VDAC1signal and found that VDAC1 was in downstream of KMT2A in the process of cervical cancer cell growth." (PMID 32436862, 2020). "We further confirmed the role of KMT2A in regulating cervical cancer growth in a mouse xenograft model." (PMID 32436862, 2020). "KMT2A is a transcriptional co-activator regulating gene expression during early development and hematopoiesis, but the role of KMT2A in cervical cancer remains unknown." (PMID 32436862, 2020). "In addition, we also analyzed the expression level of KMT2A and its clinical significance in cervical cancer using Oncomine database." (PMID 32436862, 2020). "Here, we demonstrated that KMT2A regulated cervical cancer growth via targeting VADC1." (PMID 32436862, 2020). "In cervical cancer, KMT2A revealed its function as a functional gene." (PMID 32436862, 2020). "Our results showed that KMT2A regulated cervical cancer growth by targeting VDAC1 signaling." (PMID 32436862, 2020). "We then searched Biewenga Cervix database and found that the expression of KMT2A was upregulated in cervical squamous cell carcinoma compared with the cervix uteri, and the differentiation grade of cervical cancer was negatively correlated with KMT2A expression." (PMID 32436862, 2020). "In this study, we investigated the role of KMT2A in the regulation of cervical cancer cell growth." (PMID 32436862, 2020). "Considering that VADC1 can mediate the release of apoptotic proteins and interacts with anti-apoptotic proteins and plays a key role in the process of mitochondria-mediated apoptosis, in this study we are interested in and focused on the KMT2A/VDAC1 signaling axis in cervical cancer." (PMID 32436862, 2020). "Does KMT2A also form a fusion gene to reveal its unique biological function and whether the biological function of KMT2A in cervical cancer cells was related to its methylation transferase activity or not?" (PMID 32436862, 2020). "However, because the sample number of normal tissues was limited, our analysis showed that KMT2A expression was negatively correlated with CIN stage in cervical cancer patients." (PMID 32436862, 2020).
cervical cancer (continued). "KMT2A knockdown by its specific shRNAs (sh1 and sh2) dramatically inhibited the expression of KMT2A protein in SiHa and Caski cells, and significantly suppressed cell viability and resulted in a marked reduction in the number of the colony in cervical cancer cells." (PMID 32436862, 2020). "Moreover, we found that KMT2A expression is related to the type of clinical cervical cancer." (PMID 32436862, 2020). "To identify the clinical significance of KMT2A/VDAC1 signaling axis, we detected their expression in cervical intraepithelial neoplasia (CIN) and cervical cancer tissue samples." (PMID 32436862, 2020). "The KMT2A knockdown influenced angiogenesis by reducing the expression of HIF1α and vascular endothelial growth factor (VEGF) in cervical cancer xenografts." (PMID 33302406, 2020). "To determine the possible regulation of KMT2A on VDAC1, we analyzed the effects of KMT2A and VDAC1 on cell growth, migration and apoptosis in cervical cancer cells." (PMID 32436862, 2020). "Nevertheless, the specific mechanism by which KMT2A targeted VDAC1, thereby regulating cell growth in cervical cancer cells remains to be further explored." (PMID 32436862, 2020). "In the cervical cancer tissues, the expression of KMT2A was correlation between normal tissues and SCC patients." (PMID 32436862, 2020). "Our study indicates the KMT2A/VADC1 signaling axis may be a new mechanism of cervical tumorigenesis and a potential therapeutic target for cervical cancer treatment." (PMID 32436862, 2020). "In addition, we also analyzed the expression levels of KMT2A and VADC1 in online databases and cervical cancer patients and evaluated their clinical implications." (PMID 32436862, 2020). "Moreover, analyses of Biewenga cervix database and clinical samples showed that both KMT2A and VDAC1 were upregulated in cervix squamous cell carcinoma compared with cervix uteri tissues, and their expression was negatively correlated with the differentiation grade of cervical cancer." (PMID 32436862, 2020). "In summary, our study has demonstrated that KMT2A regulates cervical cancer cell growth via targeting VDAC1 signaling, indicating that the KMT2A/VADC1 signaling axis may be a new mechanism of cervical tumorigenesis and a potential therapeutic target for cervical cancer treatment." (PMID 32436862, 2020).
chronic myelomonocytic leukemia (4 papers, 2021 to 2025). A myelodysplastic/myeloproliferative neoplasm which is characterized by persistent monocytosis, absence of a Philadelphia chromosome and BCR/ABL fusion gene, fewer than 20 percent blasts in the bone marrow and blood, myelodysplasia, and absence of PDGFRA or PDGFRB rearrangement. "RAS mutations drive proliferative chronic myelomonocytic leukemia through the lysine methyltransferase 2A (KMT2A)–Polo-like kinase 1 (PLK1) axis." (PMID 40906088, 2025).
Cornelia de Lange syndrome (4 papers, 2015 to 2024). A rare syndrome characterized by low birth weight, delayed growth, intellectual disabillity, behavioral problems, and a distinctive facial appearance (thin, arched eyebrows, low set ears, small teeth, and small nose). "Remaining Cornelia de Lange syndrome, KMT2A, KDM5C and CHD7 signatures reached 70–100% sensitivity at best with unstable performances, suffering from heterogeneous methylation profiles among cases and rare discordant samples." (PMID 37872275, 2024). "In two different works, patients with Cornelia De Lange syndrome (CdLS1, OMIM #122470; CdLS2, OMIM #300590; CdLS3, OMIM #610759; CdLS4, OMIM #614701; CdLS5, OMIM #300882)-like phenotype were found carriers of pathogenetic variants in KMT2A." (PMID 35328068, 2022).
Ewing sarcoma (4 papers, 2017 to 2023). A small round cell tumor that lacks morphologic, immunohistochemical, and electron microscopic evidence of neuroectodermal differentiation. "Both MLL1 (KMT2A) and SETD1B (KMT2G) are highly expressed by Ewing sarcoma cell lines, with expression levels comparable to those of several hematological malignancies known to be driven by MLL rearrangements and/or amplification." (PMID 27888797, 2017).
Kabuki syndrome 1 (4 papers, 2017 to 2025). "Interestingly, KMT2A-associated WSS shows phenotypical overlap with Kabuki syndrome type 1 caused by heterozygous mutations in the related gene KMT2D23." (PMID 28623346, 2017).
Kleefstra syndrome (4 papers, 2021 to 2025). A genetic disorder characterized by intellectual disability, childhood hypotonia, severe expressive speech delay and a distinctive facial appearance with a spectrum of additional clinical features. "Patients with Kleefstra syndrome are characterized by a specific alteration of the epimethylation signature, largely overlapping that of the Wiedemann–Steiner syndrome (WDSTS), associated with variants, mostly of truncating type, in KMT2A, encoding another lysine-methyltransferase." (PMID 33337535, 2021).
microcephaly (4 papers, 2020 to 2025). A congenital or acquired developmental disorder in which the circumference of the head is smaller than normal for the person's age and sex. "Clinical genetics studies identified MLL1/KMT2A pathogenic variants in patients diagnosed with either Kabuki syndrome or Rubinstein–Taiby syndrome which are characterized by ID, postnatal growth defects and microcephaly." (PMID 36845425, 2023).
prostate tumors (4 papers, 2015 to 2024). "Olfactory/ribosomal pathways and distinct cofactors, including CTCF and KMT2A, were enriched in DNA hypomethylated regions in prostate tumors from AA men." (PMID 38566104, 2024). "In a cohort of 177 laser-capture microdissected foci of prostate tumors, KMT2A expression was positively correlated with MYC activity, AR activity, and HOXB13 expression, but decreased with tumor grade severity." (PMID 36181613, 2022). "LISA-derived prediction showed enrichment of chromatin-remodeling enzymes, including CTCF and KMT2A, at hypoDMRs of prostate tumors from AA men but not EA men." (PMID 38566104, 2024).
acute megakaryoblastic leukemia (3 papers, 2020 to 2022). Acute megakaryoblastic leukemia (AMKL) is a form of acute myeloid leukemia (AML) that occurs predominantly in childhood and particularly in children with Down syndrome (DS-AMKL). "Our group described, for the first time, subtype-specific lncRNA signatures for six major cytogenetic subgroups of pediatric AML, namely, Down syndrome (DS) and non-DS acute megakaryoblastic leukemia (AMKL), inv, t, and AML with KMT2A rearrangement (t and t)." (PMID 35596093, 2022).
autism (3 papers, 2024 to 2025). Persistent deficits in social interaction and communication and interaction as well as a markedly restricted repertoire of activity and interest as well as repetitive patterns of behavior.
eosinophilia (3 papers, 2019 to 2021). "In the present study, a de novo deletion mutation in KMT2A, which is predicted to be a null allele, is identified in a boy with ID/DD, stereotypic hand movements, and blood eosinophilia." (PMID 30841869, 2019). "Besides WDSTS, deleterious variants in KMT2A were also described in association with epilepsy, primary immunodeficiency, and eosinophilia." (PMID 32641752, 2021).
hypertrichosis (3 papers, 2019 to 2025). Excessive hair growth anywhere on the body. "Kmt2a+/LSL mice demonstrated core features of WDSTS including growth retardation, craniofacial abnormalities, and hypertrichosis as well as hippocampal memory defects." (PMID 40956618, 2025).
leukocytosis (3 papers, 2013 to 2022). "Patients with positive AML1-ETO fusion gene often presented with orbital masses, while patients with abnormal KMT2A (MLL) gene were characterized by leukocytosis, CNS disease, and testicular involvement, which is consistent with the literature." (PMID 36545668, 2022). "At 10 months post bone marrow transplantation, mice with the combined Kmt2a-PTD and DNMT3A-MT showed hepatosplenomegaly and leukocytosis with a shorter latency compared to control and DNMT3A-wild-type." (PMID 32015320, 2020).
metastatic tumor (3 papers, 2022 to 2023). "For metastatic tumors from GENIE, a total of sixteen candidate genes had significantly higher SNV frequencies in MMR-d tumors, of which six genes (KMT2D (33.3%), JAK1 (28.3%), FAT1 (21.7%), ERBB4 (20.0%), KMT2A (20.0%), and MGA (20.0%)) had a SNV frequency ≥ 20% in MMR-d tumors." (PMID 36675550, 2023).
myeloid sarcoma (3 papers, 2016 to 2025). A tumor mass composed of myeloblasts or immature myeloid cells. "Chromosome deletion, KMT2A rearrangement, NPM1 mutation and RUNX1-RUNX1T1 rearrangement can be detected in more than half of myeloid sarcoma cases." (PMID 41384108, 2025).
brain ischemia (2 papers, 2018 to 2021). Diminished or absent blood supply to the brain caused by obstruction (thrombosis or embolism) of an artery resulting in neurologic damage. "The involvement of the epigenetic writer KMT2A in the molecular mechanisms elicited by MeHg is of particular interest since it has been demonstrated that it promotes neuronal apoptosis in the ischemic penumbra in an in vivo model of brain ischemia." (PMID 34899171, 2021).
congenital heart disease (2 papers, 2021 to 2024). A heart disease that is present at birth. "De novo frameshift mutation (p.Glu390Lysfs∗10) in the KMT2A gene was described in a 10-year-old boy with congenital heart disease (ventricular septal defects)." (PMID 34946970, 2021).
Hypertension (2 papers, 2025). The presence of chronic increased pressure in the systemic arterial system. "Of specific genes, lysine methyltransferase 2 A (KMT2A) was found to be central for incident hypertension, ataxia-telangiectasia mutated (ATM) for systolic blood pressure, and beta-actin (ACTB) for diastolic blood pressure." (PMID 39972178, 2025). "The most connected genes (hub genes) for the interaction network were lysine methyltransferase 2A (KMT2A) for incident hypertension, ataxia-telangiectasia mutated (ATM) for systolic BP, and beta-actin (ACTB) for diastolic BP." (PMID 39972178, 2025). "Noteworthy, KMT2A was found to be an overlapping gene in the incident hypertension, systolic BP and diastolic BP analyses which further highlights the importance of KMT2A related to blood pressure and hypertension." (PMID 39972178, 2025). "Noteworthy, KMT2A (lysine methyltransferase 2 A) is the most frequently identified gene across the analyses, as it is found for the incident hypertension, systolic BP, and diastolic BP." (PMID 39972178, 2025). "However, the exact molecular mechanisms of KMT2A-HOX influencing hypertension are unclear and only a few HOX-dependent pathways have been characterized." (PMID 39972178, 2025). "Notably, KMT2A has been identified as an upstream epigenetic regulator of hypertension onset, pointing to chromatin remodeling as a potential mediator of vascular dysfunction." (PMID 40909129, 2025). "Lastly, to the best of our knowledge none of the previous EWAS or TWAS published on hypertension related phenotypes have reported KMT2A, ATM, and ACTB among their top findings." (PMID 39972178, 2025).
hypertrichosis cubiti (2 papers, 2022). "Wiedemann–Steiner syndrome (WDSTS) is a Mendelian syndromic intellectual disability (ID) condition associated with hypertrichosis cubiti, short stature, and characteristic facies caused by pathogenic variants in the KMT2A gene." (PMID 35163737, 2022).
medulloblastoma (2 papers, 2020 to 2024). A malignant, invasive embryonal neoplasm arising from the cerebellum. "The reduction in the KMT2A levels is likely to contribute to the global reduction in the H3K4me3 levels in medulloblastoma cells, thereby repressing gene expression upon miR-193a expression." (PMID 32410663, 2020). "MiR-193a not only targeted MAX but several proliferation-related genes like CCND1, E2F1, STMN1, and chromatin modifier gene KMT2A that brought about widespread repression of gene expression in the MYC amplified Group 3 medulloblastoma cells." (PMID 32410663, 2020).
memory impairment (2 papers, 2021 to 2023). "Indeed, knockdown of KMT2A in mice similarly yielded memory impairment consistent with hippocampal dysfunction." (PMID 36062544, 2023). "To test this hypothesis, we retrieved and re‐analyzed hippocampal RNA‐seq data from mutant mice that lack the H3K4 methyltransferases Kmt2a or Kmt2b from hippocampal neurons of the adult brain and also display hippocampus‐dependent memory impairment." (PMID 33471428, 2021).
renal clear cell carcinoma (2 papers, 2022 to 2024). "It is suggested that KMT2A, 2C, 2D, 2E, 2F, and 2H may be expressed in the interstitium of renal clear cell carcinoma." (PMID 35058979, 2022).
schizophrenia (2 papers, 2019 to 2025). A major psychotic disorder characterized by abnormalities in the perception or expression of reality. "In addition to including members of the Set1-like H3K4 methyltransferase family (Kmt2a, Kmt2b, Kmt2c, and Kmt2d), these modules also encompassed rare variant genes associated with schizophrenia and ASD (Setd1a, Cacna1g, Ank3, Shank1, and Shank3)." (PMID 40102613, 2025).
thymic adenocarcinoma (2 papers, 2021 to 2023). "The thymic adenocarcinoma harbored many mutations, including ARID1A c.421del(p.A141Pfs∗91), CTCF c.517G>T(p.G173∗), KMT2A c.2155A>C(p.S719R), BAP1 c.673G>A(p.D225N), ERBIN c.2900C>G(p.S967C), LZTR1 c.2216C>T(p.S739L), POLE c.52G>C(p.E18Q), and SRC c.1334A>C(p.K445T)." (PMID 33847622, 2021).
Als (1 paper, 2025). "Once MEN1 binds, KMT2A fusion proteins relocate to the nucleus, triggering the abnormal transcription of the HOXA gene and other critical genes, such as MEIS1, for the pathogenesis of KMT2Ar Als." (PMID 39796769, 2025).
ameloblastoma (1 paper, 2025). The most common odontogenic tumor, arising from the epithelial component of the embryonic tooth and usually affecting the molar-ramus region of the mandible or maxilla. "Additional studies showed gene expression profile differences between plexiform and follicular ameloblastomas, with follicular ameloblastomas expressing variants of BRAF, KMT2D, and ABL1, while plexiform ameloblastomas expressed variants of ALK, BRAF, KRAS, KMT2D, SMO, KMT2A, and BRCA2." (PMID 38607614, 2025).
anaplastic thyroid carcinomas (1 paper, 2021). "In fact, histone methyltransferase genes (KMT2A, KMT2C, KMT2D, and SETD2) are increasingly impaired in poorly differentiated and anaplastic thyroid carcinomas." (PMID 33543394, 2021).
Autoimmunity (1 paper, 2019). The occurrence of an immune reaction against the organism's own cells or tissues. "Several genes, such as TREX1, FLI1, EVI5, IL1RAPL1, are known for their role in autoimmunity, with EVI5 being an established MS risk gene, whereas others, such as CBFB, OPCML and KMT2A, are involved in lymphoproliferative disorders (OMIM)." (PMID 30541027, 2019).
brain tumors (1 paper, 2017). "However, the role of KMT2A and its downstream signaling in brain tumors, particularly the role of epigenetic regulatory activity, remains to be clarified." (PMID 28968975, 2017).
cryptorchidism (1 paper, 2022). The failure of one or both testes of a male fetus to descend from the abdomen into the scrotum during the late part of pregnancy. "However, despite the fact that cryptorchidism has been reported in some WDSTS patients, it has never been associated with KMT2A mutations; instead, it has been associated with TASP1, which is a regulator of KMT2A." (PMID 35893049, 2022).
diabetic nephropathy (1 paper, 2025). "In diabetic nephropathy, KMT2A regulates the H3K4me3 modification of the ZEB1 gene promoter in renal tubular epithelial cells, activating its expression." (PMID 39888275, 2025).